WASL (WASP like actin nucleation promoting factor)
Description:
Regulates actin polymerization by stimulating the actin-nucleating activity of the Arp2/3 complex. Involved in various processes, such as mitosis and cytokinesis, via its role in the regulation of actin polymerization. Together with CDC42, involved in the extension and maintenance of the formation of thin, actin-rich surface projections called filopodia. In addition to its role in the cytoplasm, also plays a role in the nucleus by regulating gene transcription, probably by promoting nuclear actin polymerization. Binds to HSF1/HSTF1 and forms a complex on heat shock promoter elements (HSE) that negatively regulates HSP90 expression (By similarity). Plays a role in dendrite spine morphogenesis (By similarity). Decreasing levels of DNMBP (using antisense RNA) alters apical junction morphology in cultured enterocytes, junctions curve instead of being nearly linear.
Synonyms: N-WASP; NWASP; WASPB
Tractability: Small molecule: a structure with a bound ligand is known. Antibody: its Gene Ontology location is reachable by antibodies, with high confidence. PROTAC: ubiquitination databases record sites on it; its protein half-life has been measured.
Gene: Protein-coding gene on chromosome 7 (123,681,938 to 123,749,003, reverse strand). Ensembl gene ENSG00000106299.
Subcellular location: Cytoplasm, cytoskeleton; Nucleus; Cytoplasm
Subcellular location (Human Protein Atlas): Cytosol; Nucleoli
Pathways (Reactome):
Signal Transduction: CDC42 GTPase cycle; RAC1 GTPase cycle; RHO GTPases Activate WASPs and WAVEs; RHOJ GTPase cycle; RHOQ GTPase cycle; RHOV GTPase cycle
Developmental Biology: DCC mediated attractive signaling; EPHB-mediated forward signaling
Cell-Cell communication: Nephrin family interactions
Disease: FCGR3A-mediated phagocytosis
Immune System: Regulation of actin dynamics for phagocytic cup formation
Metabolism: NOSTRIN mediated eNOS trafficking
Vesicle-mediated transport: Clathrin-mediated endocytosis
Gene Ontology:
Molecular function: protein binding; actin binding; GTPase regulator activity; microtubule binding
Biological process: actin filament polymerization; negative regulation of lymphocyte migration; negative regulation of membrane tubulation; positive regulation of transcription by RNA polymerase II; actin polymerization or depolymerization; dendritic spine morphogenesis; formin-nucleated actin cable assembly; positive regulation of clathrin-dependent endocytosis; positive regulation of filopodium assembly; protein-containing complex assembly; vesicle budding from membrane; vesicle organization; vesicle transport along actin filament; actin cytoskeleton organization; actin filament organization; regulation of postsynapse organization
Cellular component: cytosol; extracellular exosome; nucleus; actin cytoskeleton; cytoplasm; cytoplasmic vesicle; endocytic vesicle membrane; endoplasmic reticulum membrane; microtubule cytoskeleton; plasma membrane; actin cap; cytoskeleton; glutamatergic synapse; lamellipodium
Genetic constraint (gnomAD): Loss-of-function variants: 15 observed, 41.45 expected, observed/expected ratio (o/e) 0.36, 90% interval 0.24 to 0.56. The upper end of that interval is the gene's LOEUF score, 0.56, which puts it in group 2 of 6, group 1 being the genes least tolerant of losing a copy. Missense variants: 452 observed, 547.33 expected, observed/expected ratio (o/e) 0.83, 90% interval 0.76 to 0.89. Synonymous variants: 230 observed, 194.3 expected, observed/expected ratio (o/e) 1.18, 90% interval 1.06 to 1.32.
Homologues: Orthologues: chimpanzee WASL (100% identical), macaque WASL (99% identical), pig WASL (97% identical), rabbit WASL (96% identical), guinea pig WASL (96% identical), rat Wasl (96% identical), mouse Wasl (95% identical), dog WASL (92% identical), zebrafish wasla (76% identical), tropical clawed frog wasl (72% identical), zebrafish waslb (69% identical), Caenorhabditis elegans C31C9.6 (28% identical), and 2 more. Paralogues in human: WAS (51% identical).
Diseases named in the same sentence as WASL in open-access papers:
WASL is named in the same sentence as 91 diseases in open-access papers, as found by Europe PMC text mining. Sharing a sentence is not in itself a finding about the gene and the disease. The quoted sentences say what the papers report.
breast carcinoma (27 papers, 2009 to 2025). "According to the literature, knockdown of WASL significantly reduces the number of membrane protrusions and inhibits breast cancer cell invasiveness, whereas increased WASL promotes lymph node metastasis." (PMID 28640862, 2017). "Our data identify WASL, ITGAV and several additional cytoskeleton-associated molecules as novel invasion-promoting targets of miR-142-3p in breast cancer." (PMID 26657485, 2015). "In breast cancer cells, either siRNA-depletion of WASL or miR-142-3p upregulation resulted in reduced formation of proinvasive membrane protrusions, whereas siRNA knockdown of either WASL or ITGAV, or miR-142-3p upregulation inhibited invasive growth in vitro." (PMID 32824678, 2020). "The WASL-dependent formation of invasive membrane protrusions has been identified as an important mechanism of triggering invasive behaviour of human breast cancer cells, and can be induced by several pathways including estrogen-, PDGF- and EGF-induced signaling." (PMID 26657485, 2015). "In summary, this study has revealed a novel role for miR-142-3p in regulating breast cancer cell invasiveness, which could at least partially be attributed to a targeting of WASL and ITGAV, and possibly additional cytoskeletal regulators." (PMID 26657485, 2015). "Indeed, reduction of WASL expression renders macrophages rounder and less polarized, in accordance with the morphological changes observed in our breast cancer cells." (PMID 26657485, 2015). "We experimentally validated the predicted miR-142-3p targets ROCK2, CFL2, RAC1, WASL, and ITGAV in St-T1b cells using qPCR, which is in accordance with our previous findings in breast cancer cells." (PMID 32824678, 2020).
Wiskott-Aldrich syndrome (8 papers, 2011 to 2025). Wiskott-Aldrich syndrome (WAS) is a primary immunodeficiency disease characterized by microthrombocytopenia, eczema, infections and an increased risk for autoimmune manifestations and malignancies. "WASL encodes a member of the Wiskott-Aldrich syndrome (WAS) protein family." (PMID 30255799, 2018).
melanoma (7 papers, 2012 to 2025). A malignant, usually aggressive tumor composed of atypical, neoplastic melanocytes. "In melanoma cells, DOCK10 promotes amoeboid migration by promoting the activation of CDC42 and its downstream effectors, WASl (also known as N-Wasp) and PAK2." (PMID 38793626, 2024).
lung carcinoma (6 papers, 2015 to 2023). "Studies have shown that most of the age of onset of lung cancer is over the age of 40, and the peak incidence is mainly concentrated in the age range 60–79, which is similar to the changes of WASL and WNK1 proteins in our experimental results." (PMID 37980468, 2023). "The expression of STK10 and WNK1 was increased and the expression of WASL was decreased in the urine exosome of lung cancer patients compared with normal controls, with statistically significant differences (P < 0.05)." (PMID 37980468, 2023). "Lung cancer patients had reduced expression of WASL and increased expression of STK10 and WNK1 proteins in urine exosomes compared to normal people." (PMID 37980468, 2023). "ELISA and western blotting were used to investigate the expression changes of WASL, STK10 and WNK1 in the urine exosome of lung cancer patients." (PMID 37980468, 2023). "In this study, we identified decreased expression of WASL and elevated expression of STK10 and WNK1 in the urine exosome of lung cancer patients by detection." (PMID 37980468, 2023). "Lymphocyte migration regulation related proteins were differentially expressed in the urine exosome of lung cancer patients, and WASL, STK10 and WNK1 may serve as potential biomarkers for lung cancer diagnosis." (PMID 37980468, 2023). "Changes in expression of WASL, STK10 and WNK1 may serve as potential biomarkers for lung cancer diagnosis and are of great importance for the selection of therapeutic targets in lung cancer." (PMID 37980468, 2023). "Urine exosome WASL, STK10, and WNK1 were diagnosed with lung cancer, with a combined AUC of 0.760." (PMID 37980468, 2023). "This study is the first to report the expression of WASL, STK10 and WNK1 in the urine exosome of lung cancer patients, which may serve as potential biomarkers for lung cancer diagnosis." (PMID 37980468, 2023). "This is consistent with the low expression of WASL and high expression of WNK1 protein in lung cancer patients, which may explain why the age of 60–79 years is the peak of lung cancer incidence." (PMID 37980468, 2023). "Low expression of WASL and high expression of STK10 and WNK1 represent increased lymphocyte migration, which may be closely related to lung cancer development and progression." (PMID 37980468, 2023). "But at present, the protein concentration changes of WASL, STK10 and WNK1 in the urine exosome of lung cancer patients are only preliminarily explored, and their relevance to the process of cancer cell metastasis is yet to be explored, requiring more in-depth exploration." (PMID 37980468, 2023). "We then investigated the expression of WASL, STK10 and WNK1 in lung cancer patients." (PMID 37980468, 2023).
cervical cancer (5 papers, 2018 to 2026). A primary or metastatic malignant neoplasm involving the cervix. "WASL expression was associated with the pathological stage, and it might be an independent prognostication factor in patients with cervical cancer." (PMID 34222242, 2021). "In the present study, we demonstrated that the expression of WASL was significantly correlated with the pathological stage of cervical cancer patients, and lower expression of WASL was associated with better survival of cervical cancer patients." (PMID 34222242, 2021). "However, the effect and associated mechanisms of WASL on the prognosis of patients with cervical cancer remains unclear." (PMID 34222242, 2021). "As expected, the protein level of WASL was significantly higher in cervical cancer tissues compared with that in their adjacent normal tissues." (PMID 34222242, 2021). "Based on the optimal cutoff point (10.4851), the cervical cancer samples in the TCGA-CESC study were categorized into WASL high expression group (n = 114) and WASL low expression group (n = 176)." (PMID 34222242, 2021). "We obtained high prediction accuracy and determined the correlation between the expression of WASL and the clinical characteristics of cervical cancer patients." (PMID 34222242, 2021). "Published research has demonstrated that the WASL (Wiskott–Aldrich Syndrome-Like) gene belongs to the oncogenes category and plays a significant role in tumor progression and metastasis in cervical cancer." (PMID 34368157, 2021). "To characterize the prognostic role of WASL, we performed survival analysis of cervical cancer patients based on the expression of WASL." (PMID 34222242, 2021). "Our previous study suggested that overexpression of WASL served as an oncogene in cervical cancer by promoting the invasion and migration of cervical cancer cells in vitro." (PMID 34222242, 2021). "To identify the upregulation of WASL in cervical cancer, we detected the protein level of WASL in tissue microarray by immunohistochemistry (IHC) using WASL antibodies." (PMID 34222242, 2021). "In summary, the expression of WASL was associated with the pathological stage, OS, and RFS, and it might be an independent prognostication factor in patients with cervical cancer." (PMID 34222242, 2021). "Univariate and multivariable Cox proportional hazards regression model suggested that WASL expression was an independent prognostic factor for predicting OS and RFS in cervical cancer." (PMID 34222242, 2021). "Thus, it indicated the knockdown of WASL might be correlated with biological processes such as glycolysis, TNFα signaling, mTOR signaling, and Wnt/β-catenin signaling, which, in return, might suppress the progress of cervical cancer in clinical settings." (PMID 34222242, 2021). "In addition, the univariate and multivariable Cox proportional hazards regression model suggested that WASL expression was an independent prognostic factor for predicting OS and RFS in cervical cancer." (PMID 34222242, 2021).
glioma (5 papers, 2013 to 2022). A benign or malignant brain and spinal cord tumor that arises from glial cells (astrocytes, oligodendrocytes, ependymal cells). "Of note, isolated microglia from human IDH WT gliomas expressed lower levels of WASL." (PMID 35194846, 2022). "Interestingly, expression levels of WASL were not altered in MDMs isolated from human IDH WT gliomas." (PMID 35194846, 2022). "Interestingly, while WASL expression was not altered in MDMs (p = .89), we detected lower expression levels of this gene in microglia of IDH WT gliomas in comparison to microglia from non‐tumor samples." (PMID 35194846, 2022).
virus infection (3 papers, 2017 to 2023). "Domain analysis of WASL demonstrated that its actin nucleation activity was necessary to facilitate viral infection." (PMID 31769754, 2019). "To independently assess the role of WASL during virus infection, we used a small molecule inhibitor of WASL, Wiskostatin." (PMID 31769754, 2019). "Overexpression of wild type WASL in the TNK2 KO1 A549 cells led to increased EMCV virus infection." (PMID 31769754, 2019). "The magnitude of the impact of TNK2 KO1 was greater than that of WASL KO or NCK1 KO, suggesting that TNK2 might work through additional pathways in mediating virus infection besides acting through WASL and NCK1." (PMID 31769754, 2019). "We further demonstrated that TNK2, WASL, and NCK1 function in a pathway to support EMCV virus infection with WASL and NCK1 lying downstream of TNK2." (PMID 31769754, 2019). "There are only limited studies linking WASL and NCK1 to virus infection." (PMID 31769754, 2019). "TNK2, WASL, and NCK1 are in a pathway supporting virus infection." (PMID 31769754, 2019). "In this study, we further asked whether their respective human orthologues TNK2, WASL, and NCK1 play any roles in mammalian virus infection." (PMID 31769754, 2019). "To determine whether TNK2, WASL, and NCK1 act in a common or distinct pathway for virus infection, we performed genetic epistasis analysis by generating double and triple mutant cell lines." (PMID 31769754, 2019). "WASL activation and its actin modulation are critical for EMCV virus infection." (PMID 31769754, 2019). "Since constitutively active point mutants of WASL have been described, we next tested whether overexpression of three such constructs in the TNK2 KO1 cells could further increase virus infection." (PMID 31769754, 2019).
Buruli ulcers (2 papers, 2021 to 2025). "Diseases associated with WASL include Wiskott–Aldrich Syndrome (eczema-thrombocytopenia-immunodeficiency syndrome), and WASL’s regulation of actin in the host is modified in Mycobacterium-mediated Buruli ulcers, pointing to its various roles in immune regulation and host–pathogen interactions." (PMID 33467206, 2021).
colon cancer (2 papers, 2018 to 2024). "There is evidence suggesting that different colon polyps, with or without malignant potential, exhibit similar gene expression changes in the WASL- and SRC-encoding genes, as observed in our colon cancer-related analyses." (PMID 39234565, 2024). "The results of the qPCR measurement show that the Tks4 and the WASL expression levels were significantly increased and decreased, respectively, in colon cancer samples, consistent with the database analysis results." (PMID 39234565, 2024). "Notably, among them, the expression level of WASL emerged as the most reliable marker for distinguishing between colon cancer and normal tissues." (PMID 39234565, 2024). "The expression levels of CD2AP, GRB2, WASL, and CAPZA1 are generally downregulated, while those of SRC and CTTN are upregulated in colon cancer samples compared with their levels in normal samples at the RNA and/or protein levels." (PMID 39234565, 2024). "We entered the analyzed colon cancer marker gene set (CD2AP, GRB2, WASL, SRC, CTTN, CAPZA1, and Tks4) into this tool to elucidate which cancer hallmark-related pathways are influenced by these proteins." (PMID 39234565, 2024). "This analysis revealed that the expression levels of WASL, GRB2, SRC, and Tks4 were the most important variables among the entire gene set; therefore, we conclude that the examination of these four genes should be sufficient for colon cancer diagnosis." (PMID 39234565, 2024).
allergic asthma (1 paper, 2015). A asthma with a basis in a pathological type I hypersensitivity reaction. "Furthermore, the upregulated genes (PDPK1, EZR, MYO6, CDC42BPA, OPHN1, ARF6 and WASL) identified in the present study that were enriched in the actin filament-based process require further study in order to determine whether they may be used as potential biomarkers of allergic asthma." (PMID 25633562, 2015).
COVID-19 (1 paper, 2022). A disease caused by infection with severe acute respiratory syndrome coronavirus 2. "Our data indicate that miR-142a-3p and WASL may be potential therapeutic targets for treating infectious diseases such as schistosomiasis and COVID-19." (PMID 35351657, 2022).
escherichia coli infection (1 paper, 2021). Infection with the organism Escherichia Coli. "In the studied MS patients, increased CSF nucleolin expression and SNP associations on WASL and ROCK2 genes were detected, all of which are components of the Pathogenic Escherichia coli infection pathway." (PMID 39544199, 2021).
Granuloma (1 paper, 2022). A compact, organized collection of mature mononuclear phagocytes, which may be but is not necessarily accompanied by accessory features such as necrosis. "Liver sections of WASL knockout (WASL-KO) mice infected with S. japonicum exhibited a significant increase in CD11b+Ly6G+ neutrophils surrounding S. japonicum granulomas." (PMID 35351657, 2022).
HIV-1 infection (1 paper, 2025). The type species of lentivirus and the etiologic agent of acquired immunodeficiency syndrome (AIDS). "Interestingly, MDDCs transduced with shRNA targeting N-WASP (WASL), WIP (WASPIP) and CDC42 also exhibited increased susceptibility to HIV-1 infection." (PMID 40029073, 2025).
hypothyroidism (1 paper, 2025). Abnormally low levels of thyroid hormone. "For example, genetically predicted plasma levels of ALDH2, BCL2L15, WASL, POLR2F, and ADPGK were positively associated with hypothyroidism risk, while H2BC21 and H2BC26 showed negative associations." (PMID 40868097, 2025).
Lassa virus infection (1 paper, 2019). "Furthermore, sensitivity of Lassa virus infection to Wiskostatin, a small molecule inhibitor of WASL, suggests a role of WASL in virus entry." (PMID 31769754, 2019). "The data suggesting a role of WASL in Lassa virus infection supports the notion that at least some viruses in other virus families may also depend on one or more of these genes for infection." (PMID 31769754, 2019).
ovarian carcinoma (1 paper, 2022). A malignant neoplasm originating from the surface ovarian epithelium. "This miR targets Sirtuin 1 (SIRT1) and represses the proliferation and chemoresistance in ovarian cancer and targets the Wiskott–Aldrich syndrome-like protein (WASL), Integrin Alpha V, and other cytoskeletal components." (PMID 35681531, 2022).
poliovirus infection (1 paper, 2019). An disease or disorder caused by infection with Enterovirus C. "In addition, independent Hap1 cells deficient in WASL had reduced EMCV, CVB3 and poliovirus infection (B C)." (PMID 31769754, 2019).